AURKA (aurora kinase A)
Diseases named in the same sentence as AURKA in open-access papers (continued):
Sharing a sentence is not in itself a finding about the gene and the disease.
tumor (continued). "AURKA inhibits the tumor-suppressor aspect of autophagy by suppressing AKT phosphorylation." (PMID 35317831, 2022). "Further investigation into the relationship between AURKA expression and immune examination gene expression revealed that AURKA could control the tumor-resistant pattern in most tumors by regulating the expression level of specific immune examination genes." (PMID 36685952, 2022). "AURKA is a mitotic serine/threonine-protein kinase that plays different roles in the proliferation, migration, stemness maintenance and other biological behaviours of tumour cells." (PMID 36471438, 2022). "Additionally, IHC staining showed fewer Ki-67-positive cells in AURKA-depleted tumour tissues than in the control group." (PMID 36471438, 2022). "Previous research has shown that AURKA may impact T cells, reshape the immunosuppressive tumor microenvironment, apoptosis, and hypoxia and hence contribute to immunological control, particularly CD8+ T cells that govern Th1 regulation." (PMID 36685952, 2022). "In addition, the correlation analysis highlighted that increased expression of AURKA was associated with advanced stages of LUAD and the increased number of lymph nodes containing tumor." (PMID 35520289, 2022). "The initial understanding of the influence of AURKA on the immune response comes from its application in immunotherapy, in which the AURKA epitope initiated an anti-AURKA immune response, thereby killing tumor cells with high AURKA expression." (PMID 35845594, 2022). "To further verify whether AURKA is an effective target in ESCC, we first detected the expression of AURKA transcripts in tumor and tumor adjacent tissue samples using the TCGA database." (PMID 35217647, 2022). "AURKA may also block other immune cells in the tumor microenvironment, albeit the particular mechanism is unknown." (PMID 36685952, 2022). "AURKA can regulate tumor development by modulating the cell cycle, activating anti-apoptotic signaling, inducing genomic instability, and promoting tumor invasion and tumor cell migration." (PMID 35217647, 2022). "Overexpression of AURKA has been detected in many tumor cells and tissues, including LUAD." (PMID 36311724, 2022). "In this project, two observations suggest that AURKA may promote tumor progression by regulating RNA alternative splicing." (PMID 35361747, 2022). "AURKA may also inhibit other immune cells in the tumor microenvironment, though the specific mechanism is unknown." (PMID 36685952, 2022). "Among the studied tanshinones, T1 has strong anti-tumor effects partially attributed to AURKA." (PMID 35699421, 2022). "We next explored the novel function of the abnormal expression of AURKA in tumor nuclei." (PMID 35361747, 2022). "The promoting function of AURKA on tumor growth and cell survival has been signified." (PMID 36064409, 2022). "However, some of the clinical studies of AURKA inhibitors have revealed that their use in particular molecular tumor subtypes leads to better clinical outcomes." (PMID 34050264, 2021). "Given the existence of PGC1α inhibitors and considering our findings it may also be tempting to speculate whether such drugs could synergize with AURKA inhibitors to reduce the proliferation of tumor cells." (PMID 34471141, 2021). "AURKA might operate as an oncogene during the tumor progression by activating centrosome amplification and genomic instability." (PMID 34337875, 2021). "This is consistent with our data exhibiting that downregulation of AURKA after gemcitabine-based CRT could enhance tumor response." (PMID 33573176, 2021).
tumor (continued). "This study proposed that AURKA might be involved in the hypoxia-induced proliferation of HCC tumours." (PMID 34062959, 2021). "Resistance initiated by AURKA may lead to tumor heterogeneity and promote the generation of distinct clones harboring different driving forces of drug resistance." (PMID 33451333, 2021). "Another novel substrate of AURKA with tumor-suppressive function is LKB1." (PMID 33451333, 2021). "Based on a previous study, the high level of AURKA has been associated with clinical information such as tumor stage, lymph node, but not with gender, age, and race." (PMID 34337875, 2021). "AURKA participates in tumor development by interfering with mitosis and other signaling pathways." (PMID 34539737, 2021). "Considering the in vitro findings related to the various drug combinations, involving Aurora kinase A inhibition and targeting of tumor metabolism we assessed whether these observations bear translational relevance." (PMID 34471141, 2021). "When cells were cultured in galactose, they were significantly more resistant towards reduction of cellular viability mediated by Aurora kinase A inhibitors, suggesting that tumor cells with an oxidative energy metabolism will display resistance towards AURKA inhibitor treatment." (PMID 34471141, 2021). "In addition, it was reported that GEFR promoted the activation of newly synthesised KRAS, and aurora kinase A (AURKA) avoided drug-induced tumour cells by interacting with KRAS (G12C) and the downstream protein c-RAF177." (PMID 34776511, 2021). "Overexpression of AURKA leads to centrosome hyper-amplification and tumor formation." (PMID 34244565, 2021). "Another AURKA substrate acting as a tumor suppressor is Lats2." (PMID 33451333, 2021). "Similar to the GBM models the combination treatments reduced the growth of the tumor cells more potently than the single treatments, suggesting that the approach to combine metabolic inhibitors along with Aurora kinase A blockers are likely applicable to a broader range of solid malignancies." (PMID 34471141, 2021). "In the present study, we identified that tumor-infiltrating B cells and dendritic cells are negatively correlated to the AURKA and FAM83A expression levels, which could affect the prognosis of smoking related LUAD." (PMID 33613763, 2021). "Additionally, MYC was shown to enable the tumour cells to overcome a latent cell cycle arrest in G2/M phase by directly binding AURKA." (PMID 33078469, 2020). "Moreover, MLN8237 upregulates inhibition the AURKA protein level, activates the Akt/Stat3 pathway, and increases the antiapoptosis activity of tumor-initiating cells." (PMID 31920463, 2020). "Tumours were sorted according to the expression level of AURKA or AURKB mRNA." (PMID 32138169, 2020). "Meanwhile, ZNF300 might activate CDK1 through inhibition of WEE1 and MYT1 and modulation of the MYC/AURKA/BORA/PLK1 axis to promote the tumour cells to overcome G2 arrest and enter the M phase to avoid the apoptosis induced by chemotherapeutic drugs." (PMID 33078469, 2020). "We analyzed the AURKA mRNA expression between normal and tumor tissues in our TCGA and GEO data." (PMID 33117697, 2020). "AURKA shows oncogenic activity by regulating multiple oncogenic and tumor-suppressive proteins." (PMID 32851091, 2020). "Additionally, higher expression of AurkA leads to atypical centrosome numbers and the generation of aneuploidy which can lead to cell proliferation, tumor progression, and metastasis." (PMID 35047986, 2020).
tumor (continued). "In tumor cells, AURKA induces cell proliferation, survival and drug resistance through interacting with oncogenic pathways, such as MYC, PKC/RAF/MEK/ERK, BCR/ABL, NF-κB, Wnt/β-catenin or the PI3K/AKT pathways, modulating pro-apoptotic (BCL2, MCL1) and anti-apoptotic (BAX, BIM, PUMA, APAF) proteins." (PMID 32018226, 2020). "Thus, the effect of AURKA-targeted inhibition of tumor growth plays roles in both the deactivation of AURKA activity and the decrease in the AURKA protein level." (PMID 31920463, 2020). "Next, we checked the level of AURKA in the tumor tissue from xenograft mice." (PMID 31920463, 2020). "Regarding other clinicopathological characteristics of LADC, the distribution frequency of AURKA SNP rs6024836 was numerically higher in the mutated EGFR group with a lower tumor T status, absence of lymph node involvement, and negative distant metastasis." (PMID 33050100, 2020). "Accordingly, the overexpression of AURKA was found as an independent adverse factor associated with shorter overall survival in NSCLC and, thus, may serve as a prognostic indicator in this tumor." (PMID 33202573, 2020). "As N-Myc suppresses AR signaling and drives lineage plasticity, tumor aggressiveness, and AR-independent progression in PCa, AURKA interacts with N-Myc through protein-protein interactions (PPI) and forms a complex to protect N-Myc from Fbxw7-mediated proteasomal degradation." (PMID 33167327, 2020). "One the other hand, AURKA plays a pivotal role in tumor survival by provoking Bcl-2 and MCL-1, and anti-apoptotic factors levels, blocking Bax, Bim, PUMA apoptotic mediators activity, along with disruption of the mammalian Target of Rapamycin (mTOR) autophagy pathway." (PMID 32469983, 2020). "Indeed, we found that combined inhibition of EGFR and AURKA is efficacious in YU-1089 cells that were established from patient tumor progressing to olmutinib." (PMID 31882684, 2019). "TTK, AURKA, BUB1, CDK1 and NEK2 were fundamental kinases with high node degree, which may be required for maintaining the molecular signals underlying tumor progression." (PMID 30598639, 2018). "Accumulating evidence with respect to the studies of oncogene has proved that AURKA, belonging to a family of mitotic kinases that maintain chromosomal stability, could promote tumor cell proliferation, diving tumorigenesis and tumor progression." (PMID 30547784, 2018). "Both AURKA and p27 were highly expressed in the tumor tissues compared with the adjacent tissues." (PMID 30013101, 2018). "Higher levels of AURKA expression were correlated with higher tumor grade, and poorer prognosis." (PMID 28183295, 2017). "Furthermore, we subcutaneously injected MDA-MB-231 cells harbouring stably integrated inducible AURKA knockdown short hairpin RNA (shRNA) constructs into nude mice and evaluated their effects on tumour growth." (PMID 28114286, 2017). "In contrast, overexpression of AURKA in UC5 cells (low expression of AURKA) resulted with down-regulation of NNMT Since NNMT is implicated in invasion and metastases, these results directed our attention to the potential role of AURKA in tumor progression." (PMID 28102366, 2017). "All in all, these observations indicate that FOSL1 links KRAS oncogene to genes involved in mitotic fitness, and suggest that AURKA and TACC3 may partially mediate the ‘synthetic sensitivity' of mutant KRAS tumours to FOSL1 loss." (PMID 28220783, 2017).
tumor (continued). "To address the question whether AURKA FISH test can predict tumor recurrence we used 224 samples from patients with superficial bladder cancer that were followed for recurrence." (PMID 28102366, 2017). "The present study demonstrated that the AURKA rs2064863 polymorphism was associated with a high risk of stage III/IV OSCC but not with tumor size, metastasis to the lymph node and distant organs, or cell differentiation." (PMID 28152093, 2017). "In addition, inducible shRNA-mediated knockdown of AURKA in A549 cells decreased tumor growth in vivo." (PMID 26842935, 2016). "Similarly, there was a positive association between AURKA and RACGAP1 gene expression in the tumor‐adjacent (r = 0.425, P = 0.003) and the tumor‐distant mucosa (r = 0.699, P < 0.001)." (PMID 26778597, 2016). "We also inhibited members of the FAK/PI3K/Akt pathway and found that AURKA might reverse tumor cell dormancy and contribute to LSCC metastasis and recurrence via FAK/PI3K/Akt pathway activation." (PMID 27356739, 2016). "Here, we observed that AURKA overexpression could revive dormant tumor cells to promote tumor metastasis." (PMID 27356739, 2016). "Importantly, overexpression of AURKA and TPX2 has been linked to tumor development at different levels." (PMID 27827897, 2016). "We hypothesized that AURKA might promote FAK/PI3K/Akt pathway activation to regulate LSCC tumor metastasis." (PMID 27356739, 2016). "Indeed, AURKA is well known to play an important function in tumor development, progression, and patient survival." (PMID 26466313, 2015). "Together, the results of this study support the hypothesis of a causative link between altered function of AURKA-HMMR-TPX2-TUBG1 and breast carcinogenesis in BRCA1/2 mutation carriers." (PMID 25830658, 2015). "On the other hand, it was reported that hypoxia and hypoxia-inducible factor-1 (HIF-1) are important in the tumor microenvironment and could regulate AURKA at the transcriptional level." (PMID 25987188, 2015). "Indeed, the single targeting of AURKA with siRNA or MK-5108 inhibited uLMS cell proliferation in vitro and decreased the number and size of tumor implants in vivo." (PMID 26576131, 2015). "Germline polymorphisms in the mitotic checkpoint proteins Aurora kinase A and BUB1 kinase B may have furthered tumour growth." (PMID 26102504, 2015). "For instance, hsa-let-7b-5p is observed as tumor suppressive, the reason could be either or both: The targets of hsa-let-7b-5p included well-known oncogenes AURKA and BIRC5, or the targets involved much more amplified genes." (PMID 26099552, 2015). "Importantly, several studies indicated that AURKA overexpression directly leads to malignant transformation and tumor formation." (PMID 25987188, 2015). "Based on the recent understanding of TOB1, a putative role of TOB1 may be associated with tumor suppressor SMAD4 and oncogenic CTNNB-mediated signaling, likely including SMAD4-mediated suppression of AURKA-CTNNB activation." (PMID 26694352, 2015). "However, only tumor size larger than 11.5 cm and AURKA overexpression were identified as independent unfavorable prognostic factors for OS in the multivariate analysis." (PMID 24901229, 2014). "Here, we propose that AURKA represents a rational therapeutic target for MPNSTs and that the sensitivity of these tumours to AKI may be regulated by gene dosage and expression of HMMR/RHAMM." (PMID 23328114, 2013).
tumor (continued). "Similarly, increased 1-year and 2-year survival was seen among those patients with KRAS wild-type tumours and high AURKA-CN compared with patients with KRAS wild-type tumours and low AURKA-CN (1 year: 96% vs 75% P<0.0001; 2 year: 93% vs 28% P<0.0001)." (PMID 22240781, 2012). "In addition, AURKA RNA levels correlated with histological grade (P<0.001), tumor size (P<0.001) and HER2 (P<0.001)." (PMID 23186136, 2012). "Thereforethe inhibition of the activity of Aurora Kinase A could lead to the tumor cell apoptosis instead of malignant proliferation." (PMID 22809428, 2012). "However, among the 20 tumours with high AURKA-CN, 9 were found to have positive staining (P=0.06 for difference between high and low AURKA-CN tumours)." (PMID 22240781, 2012). "Similarly to PFS, the longer OS for patients with high AURKA-CN tumours was particularly pronounced in the KRAS wild-type patient population." (PMID 22240781, 2012). "In all, 68% of tumour exhibited high AURKA-CN, and 29% had a KRAS mutation, without correlation between the two." (PMID 22240781, 2012). "We also identified that the AURKA transcript over-expression was significantly associated to tumor de-differentiation, and its activity was not directly associated to either epithelial marker expression or to enhanced cell motility." (PMID 21718475, 2011). "The expected model size with the highest performance level consists of 10 of the most robust predictive variables and is comprised of four clinico-pathological variables and six additional proteins: nodal status, tumor size, AURKA, BCL2, age, CD68, HER2, MYBL2, CCNB1 and GSTM1." (PMID 20809974, 2010). "Screening tumor samples for AURKA, TPX2, and MYBL2 expression is feasible, and could be incorporated into design of clinical trials for Kinesin-5i response." (PMID 19259408, 2008). "Although the effect of alisertib on the immune microenvironment is not fully understood, these responses of the immune microenvironment to AURKA inhibition may contribute to the suppression of tumor progression and increased responsiveness to anti–B7-H3 therapy." (PMID 39928563, 2025). "Moreover, AURKA is centrally involved in maintaining tumor stem cell-like properties." (PMID 40949156, 2025). "Moreover, the results showed that AURKA may be involved in the compensatory mechanism of maintaining tumor aggressiveness after ANDROGEN deprivation therapy." (PMID 40718709, 2025). "Combining AURKA inhibition with immunotherapies such as checkpoint blockade or novel immune cell-based treatments may offer improved therapeutic outcomes by simultaneously disrupting the immunosuppressive tumor microenvironment." (PMID 38995006, 2024). "In addition, AURKA was observed to regulate the infiltration levels of various immune cells in the NB tumor microenvironment, resulting in remodeling of the immunosuppressive tumor microenvironment." (PMID 39585848, 2024). "Finally, AURKA may play an important role in the regulation of the tumor immune microenvironment; however, additional research studies are warranted to identify the potential mechanism involved in this process." (PMID 38903715, 2024). "Our patient tumor sequencing data shows the overexpression of AURKA and AURKB (average Z-score = 2.33 and 2.18, respectively); the result that Panobinostat decreases AURKB shows again that it is targeting another pathway which may be playing an important role in tumor progression." (PMID 39518006, 2024). "Additionally, we delved into the relationship between AURKA and the tumor microenvironment." (PMID 37965456, 2023). "Finally, 3D spheroid cultures provided evidence that Aur-I (AURKA inhibitor) suppressed the growth of EAC spheroids, implying that high AURKA expression might be associated with an increased risk of tumor metastasis in EAC." (PMID 37965456, 2023).